TRIM28 (tripartite motif containing 28)
Diseases named in the same sentence as TRIM28 in open-access papers (continued):
Sharing a sentence is not in itself a finding about the gene and the disease.
cancer (continued). "Therefore, TRIM28 is the first potential epigenetic regulator that promotes cell metastasis and may serve as a therapeutic target against cancer in combination with other traditional strategies." (PMID 28851455, 2017). "Tripartite motif-containing protein 28 (TRIM28) is thought to regulate the dynamic organization of chromatin structure by influencing epigenetic patterns and chromatin compaction and may thus play an important role in the homeostasis of cancer cells." (PMID 27845900, 2017). "Also, better understanding of TRIM28 involvement in carcinogenesis may help to answer whether TRIM28 possess the potential to become a new anti-cancer target." (PMID 28851455, 2017). "Therefore, TRIM28 contributes to the negative regulation of E2F1 and may serve as a partial backup to prevent E2F1-mediated apoptosis in cancer cells, suggesting that TRIM28 acts as a pro-tumorigenic factor." (PMID 28851455, 2017). "Recent studies have suggested that Trim28 might play a role in cancer development and metastasis." (PMID 24983967, 2014). "The interaction between TRIM28 and MDM2 contributes to the suppression of apoptosis in cancer cells." (PMID 39534556, 2024). "Our results indicated that higher gene expression levels of RELA were positively correlated with increased IC50 values of cancer therapy drugs, while UBA2, TRIM28, TRIM27, and CAPN3 showed opposite correlations." (PMID 38407971, 2024). "TRIM28 was first identified as a STAT-binding partner and frequent crosstalk between IL-6/STAT3 and NF-κB has been observed in cancer progression." (PMID 37443302, 2023). "We also observed that TRIM28 expression is positively correlated with PD-L1, TBK1, and IRF1 levels in various cancers." (PMID 37357254, 2023). "Our previous studies indicated that TRIM28‐dependent ubiquitination and USP44‐dependent deubiquitination of FBP1 regulated its stability in cancer cells." (PMID 34854226, 2022). "Among TRIM28 ubiquitination targets, the 5’ AMP-activated protein kinase (AMPK), which regulates the “metabolic switch” in cancer cells, is known for impairing cancer stem-like phenotype acquisition." (PMID 33810347, 2021). "In those cancers, high BOK and low TRIM28 mRNA levels correlated with increased survival, and low BOK and high TRIM28 levels with decreased survival." (PMID 33043006, 2020). "Of note, TRIM28 and BOK levels were found to be negatively correlated in selected cancers such as hepatocellular carcinoma and kidney cancer." (PMID 33043006, 2020). "In theory, BORG induces the metastatic colonies of potent BC cells by activating the transcriptional repressive activity and localization of TRIM28, which combines with BORG and leads to a great amount of changes in cancer progression." (PMID 31214490, 2019). "BORG induces the metastatic colonies of potent BC cells by activating the transcriptional repressive activity and localization of TRIM28, which combines with BORG and leads to a great amount of changes in cancer progression." (PMID 31214490, 2019). "Moreover, TRIM28 has been demonstrated to regulate EMT gene expression (CDH1 encoding E-CADHERIN and CDH2 encoding N-CADHERIN) through modification of histones of target gene promoters, further implying its role in acquisition of highly aggressive mesenchymal phenotype of cancer cells." (PMID 28851455, 2017). "Intriguingly, target genes of all four factors (Cnot3, Trim28, c-Myc, and Zfx) are enriched for cancer genes (as determined by Ingenuity Pathway Analysis) supporting the idea that regulatory networks controlling self-renewal in stem cells may also be active in certain cancers." (PMID 28851455, 2017). "It is known that Trim28 expression and TGF-β signaling are both increased in a variety of cancers including lung." (PMID 24983967, 2014).
cancer (continued). "The Tripartite motif-containing 28 (TRIM28/TIF1b/KAP1) is a key transcriptional co-repressor protein that represses ERV expression in many cell types including embryonic stem cells, neural progenitor cells, differentiated adult cells, and cancer cells." (PMID 41508128, 2026). "Tripartite motif-containing 28 (TRIM28/TIF1b/KAP1) is a key transcriptional co-repressor protein that represses ERV expression in many cell types including embryonic stem cells, neural progenitor cells, differentiated adult cells, and cancer cells." (PMID 41508128, 2026). "Thus, this review will focus mainly on the crosstalk of the signaling pathways in cancer development, especially the ones that involve widely studied TRIM proteins, i.e., TRIM28, TRIM25 and TRIM59." (PMID 39451518, 2024). "With regard to function, perturbation of Trim28 (overexpression or depletion), however, did not affect cancer cell growth or cell cycle." (PMID 38963708, 2024). "TRIM28 (tripartite motif protein 28) was initially believed to be a transcription inhibitor that plays an important role in DNA damage repair (DDR) and in maintaining cancer cellular stemness." (PMID 39100077, 2024). "Unlike normal cells, many human cancers and cancer‐derived cell lines exhibit variable, yet generally elevated levels of endogenous full‐length L1 mRNA expression, even in the presence of increased TRIM28 activity." (PMID 39534556, 2024). "TRIM28 (RNF96) plays pleiotropic biological functions, such as silencing target genes, facilitating DNA repair, stimulating cellular proliferation and differentiation, and contributing to cancer progression." (PMID 38947392, 2024). "TRIM28 operates in inhibiting E2F transcription factor 1 (E2F1) and may act as a partial backup mechanism to impede E2F1‐induced apoptosis in cancer cells." (PMID 39534556, 2024). "The interaction between TRIM28 and MDM2 plays a role in suppressing apoptosis of cancer cell." (PMID 36756159, 2023). "Having demonstrated that TIAM1 and TRIM28 promote EMT via downregulation of E-cadherin, and that they directly repress protocadherins, which themselves can regulate EMT in cancer, we analyzed the functional significance of this regulation on NSCLC cell migration." (PMID 37748077, 2023). "Our analysis revealed a significant elevation of TRIM28 expression in cancer samples compared to adjacent non-tumor tissues across multiple cancer types." (PMID 37865804, 2023). "Similar to TRIM28, the exact mechanism of BRD4‐associated cancer stemness‐high phenotype is not clear, although unequivocally it depends on bromodomain activity." (PMID 35049055, 2022). "TRIM11, TRIM27, TRIM28 and TRIM59 have higher expression in almost all cancers." (PMID 36461099, 2022). "TRIM28 was previously shown to form a cancer-specific E3 ubiquitin ligase together with MAGE-A3/6 proteins for proteasomal degradation of AMPK, a master regulator of metabolic/energy homeostasis and mitochondrial biogenesis in cancer cells." (PMID 36304339, 2022). "Immunohistochemical results further demonstrate the role of TRIM28 and TRIM58 in cancer." (PMID 36461099, 2022). "The TRIM28 protein was shown to have a crucial impact on self-renewal ability and maintenance of pluripotency in mouse and human ESC, as well as in human cancer cells." (PMID 34440702, 2021). "Trim28 is indispensable for the reprogramming of mouse fibroblasts into iPSC and in stemness maintenance in mouse and human PSC, as well as in human cancer cells." (PMID 34440702, 2021).
cancer (continued). "TRIM24, TRIM28, TRIM33, and TRIM66 form the transcriptional intermediary factor 1 (TIF1) family of chromatin-binding proteins that are involved in DNA damage response (DDR) and show significant involvement in different cancer types." (PMID 33923045, 2021). "As such, TRIM28 RING and PHD domains may be considered new targets for cancer therapy, e.g., by designing a drug inhibitor complementary to selected domains." (PMID 34440702, 2021). "TRIM32, TRIM28, and TRIM44 promote cancer progression by activating β-catenin signaling." (PMID 32802046, 2020). "The interactions of the Wnt/β-catenin pathway and other members of the TRIM protein family, such as TRIM29, TRIM28, TRIM32, TRIM33, and TRIM44, may play important roles in the development of human cancers." (PMID 32802046, 2020). "TRIM28 is an essential component of the fibroblast transcription site-1 activator transcription complex required for induction of EMT and has been shown in cancer to further contribute to EMT via regulation of E- and N-cadherins." (PMID 29631612, 2018). "Our findings show that TRIM28 is necessary for MAGEC2 expression in cancer cells, and TRIM28 may serve as a new potential target for immunotherapy of cancer." (PMID 30309319, 2018). "Additional T-47D luminal cancer cell line poor in CD44+/CD24−/low population was also tested in vivo presenting no impact of TRIM28 downregulation on xenograft growth." (PMID 27845900, 2017). "Thus, our data not only identify TRIM28 as an E3 ligase of FBP1, but also suggest that TRIM28-regulated reprogramming of cancer cell metabolism is mediated, at least in part, through FBP1 degradation in HCC cells." (PMID 28394358, 2017). "Surface marker expression is of particular interest due to its potential applications in both cancer diagnostics and targeted therapy; therefore, we next analyzed whether the knockout of CD133 or its epigenetic regulator TRIM28 affects the membrane proteome of Caco2 cells." (PMID 41303350, 2025). "Since cancer stem cells (CSCs) exhibit high proliferative and migratory potential, it is important to assess the impact of knocking out CD133, the most commonly used classical surface marker of CSCs, and its expression regulator TRIM28 on these fundamental cellular functions." (PMID 41303350, 2025). "However, the prognostic and immunotherapeutic role of TRIM28 in human cancer has not been elucidated." (PMID 37781084, 2023). "However, the mechanism by which TRIM28 alterations affect the prognosis of human cancers has not been examined." (PMID 37781084, 2023). "Therefore, there are at least two potential modes of action proposed for TRIM28 acting as a facilitator of cancer stemness (in accordance with KRAB-ZNFs): (i) TRIM28 switches off the expression of differentiating genes and/or (ii) TRIM28 enhances the expression of pluripotency markers." (PMID 36674511, 2023). "Although a similar trend is not clearly observed with the length of the L1 inserts in cancer samples, this can be explained by the presence of L1 inserts generated prior to the increase in the TRIM28 expression in any given sample or a potential heterogeneity in TRIM28 expression in single cells." (PMID 37070200, 2023). "In addition to the TRIM28 expression levels, other inclusion criteria for the two groups within each cancer type are sex, age, race and availability of WGS bam files generated from blood/normal and cancer samples collected from the same patient." (PMID 37070200, 2023). "The multi-domain of TRIM28 contributes to the regulation of a variety of cellular processes such as cell proliferation, apoptosis, protein degradation, autophagy and EMT, and several reports have shown the positive clinical relevance between TRIM28 expression levels and specific cancer types." (PMID 35743282, 2022).
cancer (continued). "Especially, the engagement of BRD4, a member of BET transcriptional coactivators, as well as the role for TRIM28—a transcriptional co‐repressor, known to mediate E3 SUMO/ubiquitin ligase activity, have been well established in mediating the self‐renewal properties of cancer stem cells." (PMID 35049055, 2022). "Zscan4 is only expressed in two-cell embryos and a small proportion of embryonic stem cells at a given time, suggesting that it may not be the target for TRIM28 to regulate the ALT pathway in cancer cells." (PMID 34330324, 2021). "As TRIM28 emerges as a guard of the intrinsic state of cell differentiation, maintaining stem cells and somatic cells in the pluripotent and differentiated state, respectively, its’ role in cancer stem cell maintenance was not surprising." (PMID 33076560, 2020). "In addition, TRIM28 has been identified as a binding partner of class I MAGE proteins, which are able to exploit the E3 ligase activity of TRIM28 in the progression of a variety of cancers." (PMID 31028095, 2019). "The TRIM28/KRAB complex triggers epigenetic repression of specific target genes and thus might be involved in alterations occurring in cancer cells." (PMID 30444046, 2019). "Specifically, Trim28 expression is up-regulated in cancer tissues compared to normal tissues." (PMID 24983967, 2014). "These patient-based findings agree with our findings in HeLa cells using LEAP assays as well as a ruler PCR assay and demonstrates that variation in TRIM28 expression levels in vivo may influence the length of de novo L1 inserts in at least three different cancer types as well as in both sexes." (PMID 37070200, 2023). "Furthermore, TRIM28 may influence immune, ESTIMATE, and stromal scores in a variety of cancers." (PMID 37781084, 2023). "Also, TRIM28 might act (c) by targeting for proteasomal degradation (through RING‐mediated E3 ubiquitin ligase activity) various proteins, that is, AMPK, a “metabolic switch” that attenuates cancer stemness." (PMID 35049055, 2022). "In addition, overexpression of miR-140-5p could inhibit proliferation, migration, and invasion and promote apoptosis in cancer by downregulating MAPK1, TRIM28, and YES1, further regulating levels of cleaved caspase-3, Bcl-2, and Bax, and blocking nuclear transport and Wnt/β-catenin signaling." (PMID 34479600, 2021). "But only three cancers—KICH, KIRP, and PAAD—show no discernible difference in TRIM28 expression between normal and cancerous samples." (PMID 39534556, 2024). "A simultaneous increase in the expression levels of NEK9, TRIM28 and CTTN was found in metastatic GC lesions compared with paired non-cancerous tissues and primary cancer lesions via IHC and Multiplex IHC." (PMID 37443302, 2023). "In the present study, a simultaneous increase in the expression levels of NEK9, TRIM28 and CTTN was found in metastatic GC lesions compared with paired non-cancerous tissues and primary cancer lesions." (PMID 37443302, 2023). "This confirmed previously reported relation between TRIM28 level and cancer dedifferentiation status and suggested a specific role for TRIM28 (and not other close-related TRIM family members) in cancer reprogramming." (PMID 33076560, 2020).
tumor (111 papers, 2014 to 2026). "TRIM28-mediated predisposition appears to act even more simplistic with biallelic mutations in both nephrogenic rests and tumor samples as the only genetic change, but the determinants of progression from nephrogenic rest to WT remain unresolved." (PMID 40340749, 2025). "TRIM28 acts as a key transcriptional co-repressor involved in epigenetic regulation and has been implicated in shaping the tumor immune microenvironment by controlling gene expression programs relevant to immune escape." (PMID 41303350, 2025). "We thereby identified 15 children with a WT1 and 6 children with a TRIM28 germline mutation, interrogating their tumours by whole genome or exome sequencing, methylation arrays and RNA sequencing." (PMID 39665570, 2025). "The median age of diagnosis segregated by predisposition, with classical predisposition variants (e.g. in WT1 or TRIM28) generating tumours at a younger age than in the control group (10 vs. 36 months)." (PMID 39665570, 2025). "We found significant mutations in TRIM28 in multiple tumor tissues, especially in endometrial cancer (EC), with a mutation probability of 6.25%." (PMID 39100077, 2024). "Nevertheless, the molecular mechanism underlying tumor-specific elevation of TRIM28 remains largely uncharacterized." (PMID 39532800, 2024). "TRIM28 (aka KAP1) is an E3 ubiquitin ligase that has garnered significant attention in the area of cancer biology as its expression is linked with tumor progression." (PMID 38495890, 2024). "Collectively, these data show that TRIM28 is intimately associated with tumor immune cell infiltration." (PMID 37781084, 2023). "Understanding the regulation of MDSC recruitment and function by TRIM28 provides crucial insights into the association between TRIM28 signaling and the development of an immunosuppressive tumor microenvironment." (PMID 37865804, 2023). "Given that tumor-associated TRIM28 induces CD8+T cell exhaustion through NF-κB signaling, we sought to assess RIPK1 as a potential therapeutic target in combination with immune checkpoint blockade." (PMID 37865804, 2023). "All blood germline TRIM28-associated WT were found to have normal tumor chromosome 11p15.5 copy number with ROI." (PMID 38110397, 2023). "Across all tested tumor types, only the TRIM28-associated transcription profiles were consequently enriched with gene expression signatures representing a stem-like phenotype." (PMID 33810347, 2021). "Only TRIM28-associated transcriptome profiles are significantly enriched with targets for the c-Myc transcription factor across most TCGA tumor types, which strongly reflects the mRNA-SI gene signature enrichment results." (PMID 33810347, 2021). "The aim of this study was to explore potential association of TRIM28 with tumor features and survival." (PMID 33817325, 2021). "TRIM28 was also enriched in GB (tumour) core and associated with the expression of stem cell genes, but was not prognostic for overall survival." (PMID 34500575, 2021). "Conversely, loss-of-function TRIM28 mutations can predispose children to Wilms’ tumour, the most common type of renal cancer in paediatrics, suggesting a tumour suppressor role in this context." (PMID 32731534, 2020). "Here, we perform differential epithelium-stroma proteomic network analyses to characterize signaling pathways associated with TRIM28 within the tumor microenvironment." (PMID 29631612, 2018). "The remarkable genomic simplicity of tumours 37T and W117 provides strong evidence that loss of TRIM28 is the sole driver of tumorigenesis in these cases." (PMID 29912901, 2018). "Unsupervised hierarchical clustering of tumour samples using 25,387 probes showed that the two TRIM28-mutated tumours for which RNA was available (37T and W117) clustered together." (PMID 29912901, 2018).